ERF (ETS2 repressor factor)
Diseases named in the same sentence as ERF in open-access papers (continued):
Sharing a sentence is not in itself a finding about the gene and the disease.
Chitayat syndrome (2 papers, 2019 to 2023). "Elsewhere, a specific heterozygous ERF missense p.(Y89C) substitution has been found to cause Chitayat syndrome in four unrelated probands and one parent with hyperphalangism, characteristic facies, hallux valgus, and bronchomalacia." (PMID 30758909, 2019). "ERF is associated with autosomal dominant craniosynostosis 4 (OMIM: 600775) and Chitayat syndrome (OMIM: 617180)." (PMID 38031187, 2023).
lung carcinoma (2 papers, 2018 to 2019). "A previous report proposed that an evolutionarily conserved network that regulates EGFR-induced miR-7 expression may target ERF to modulate cell growth in human lung cancer." (PMID 30988068, 2019). "EGFR activates miR-7 through the Ras/extracellular signal-regulated kinase (ERK)/Myc pathway and inhibits ETS2 repressor factor (ERF, a transcriptional repressor of V-ets avian erythroblastosis virus E26 oncogene homolog 2 (Ets2)), thereby promoting cell growth and the occurrence of lung cancers." (PMID 30400981, 2018).
melanoma (2 papers, 2023 to 2025). A malignant, usually aggressive tumor composed of atypical, neoplastic melanocytes. "In melanoma, several ETS TFs, including FLI1, SPI1, ELF4, ETV7, SPIB, and SPIC, are expressed at higher levels in Cluster A patients, whereas ETV5, ETV4, ELK1, ERF, and ETV2 showed increased expression in Cluster B patients." (PMID 41502516, 2025).
nematode infection (2 papers, 2016 to 2021). "In this study, we found that expression of genes encoding ERF (unigene 0004006) and MYB (unigene 0000628) transcription factors involved in plant hormone signaling was positively correlated with nematode infection." (PMID 34271854, 2021). "Previously, comparative transcriptome analysis revealed that, for ramie, drought stress and root lesion nematode infection regulated 24 TF genes (containing three NACs, two MYBs, and one EFR) and 40 TFs genes (containing 10 bHLHs, five MYBs, two NACs, and one ERF), respectively." (PMID 27034936, 2016).
prostate adenocarcinoma (2 papers, 2023 to 2024). "Consistent with being an AR interacting protein that confers tumor suppressor activity, ERF chromatin occupancy overlapped with AR binding sites by 28% in normal prostate organoids but not in a prostate adenocarcinoma cell line." (PMID 38317241, 2024).
cyst (1 paper, 2024). A sac-like closed membranous structure that may be empty or contain fluid or amorphous material. "The AP2/ERF is another key TF family in ethylene signaling pathway involved in plant-cyst nematode interactions such as RAP2.3, GmEREBP1 and RAP2.6." (PMID 39295536, 2024).
developmental delays (1 paper, 2023). "Similar to CIC, loss of ERF has been linked to dysregulation of the cell cycle, developmental delays, and intellectual disability." (PMID 37345142, 2023).
gastric carcinoma (1 paper, 2025). A carcinoma that arises from epithelial cells of the stomach. "The level of mRNA expression of ETS family members in gastric carcinoma tissues was also variable with ELF3, ETS2, EHF, ERF and ELF1 being the family members with the highest expression." (PMID 41425714, 2025). "mRNA expression levels of ETS family members in gastric carcinoma tissues were variable, with ELF3, ETS2, EHF, ERF, and ELF1 being the family members with the highest expression." (PMID 41425714, 2025).
leukemia (1 paper, 2025). A malignant (clonal) hematologic disorder, involving hematopoietic stem cells and characterized by the presence of primitive or atypical myeloid or lymphoid cells in the bone marrow and the blood. "The final top gene list included both known cancer-associated genes (e.g., ERF) and genes with previously unknown relevance to leukemia, such as PSG genes." (PMID 40806565, 2025).
metastatic tumor (1 paper, 2022). "Among the genes covered by this study, considering the 19 that are affected by alterations of any kind, only NF1 and ERF are found to be altered with significantly different frequencies between primary and metastatic tumor (adjusted p 0.016 and 0.025, respectively, FDR < 0.05 with 19 comparisons)." (PMID 36358725, 2022).
sterility (1 paper, 2022). "Although there is no direct evidence to prove the relationship between ERF and sterility, we think that the relation between sterility and ERF family genes deserves further study." (PMID 35806189, 2022).
stomach adenocarcinoma (1 paper, 2022). "Beyond PCa, we and others have observed that CIC and ERF are co-deleted in a subset of stomach adenocarcinoma." (PMID 36383412, 2022).
thalassemia (1 paper, 2024). An inherited blood disorder characterized by a decreased synthesis of one of the polypeptide chains that form hemoglobin. "To uncover the mechanism underlying the hypermethylation of ERF promoter, we performed RNA sequencing in β0/β0-thalassemia patients and identified an upregulated long noncoding RNA (RP11-196G18.23) associated with HbF production." (PMID 38218889, 2024).
Tracheomalacia (1 paper, 2022). "Regarding the patient’s tracheomalacia, although some genes responsible for this trait are present in the region, such as ERF or LTBP4 on chromosome 19q13.2, none of the genes that were haploinsufficient in our patient seemed to be responsible for this feature." (PMID 35205257, 2022).
infection (57 papers, 2012 to 2026). The state of being infected such as from the introduction of a foreign agent such as serum, vaccine, antigenic substance or organism. "Although these findings collectively suggest an important link between AP2/ERFs and pathogenic infection, few disease-related ERF genes have been reported in banana plants." (PMID 38542394, 2024). "Among over 100 members in Arabidopsis and rice, the ERF genes in group IX have often been associated with defence gene expression in response to pathogen infection." (PMID 28934298, 2017). "Indeed, several genes encoding AP2/ERF members were strongly up-regulated after HSt feeding (16 out of 20), while only two out of seven genes were up-regulated in response to FDSt infection." (PMID 31242866, 2019). "In addition, differentially expressed genes encoding transcription factors from the MYB, NAC, WRKY, ERF, and bHLH families were highly expressed, they could be the key responsive factor in the response of cherry to infection by A. alternata." (PMID 36844070, 2023). "In our study, RT-qPCR validation aligned with RNA-seq data, showing a significant downregulation of six ERF genes upon infection with the ΔCgmas2 mutant at 96 hpi." (PMID 41596494, 2026). "By contrast, seven genes, including two AP2 and five ERF genes, constitutively expressed in the stems, were downregulated upon infection." (PMID 40941858, 2025). "In rice, infection by Magnaporthe grisea can induce the expression of ERF genes such as OsBIERF1, OsBIERF3, OsBIERF4, and OsEBP2." (PMID 39062711, 2024). "A previous study in wheat found that an ERF gene known as TaPIEP1 is induced upon infection, leading to enhanced resistance against Bipolaris sorokiniana through overexpression." (PMID 38542394, 2024). "In this study, few members of the ERF TFs, which are involved in JA-responsive gene regulation, were transcriptionally altered by SA treatment or Cmm infection." (PMID 38434116, 2023). "Briefly, most of the core genes were related to the redox state, ERF, etc. of 4-day treated sample of FocTR4 infection." (PMID 37948570, 2023). "Transcription factors classified as BBX-DBB, BBX-CO, DOF, MYB, REVEILLE, bZIP, NPL, ERF, AP2, NAC, and bHLH were revealed as differentially expressed in the susceptible cultivar during the BBTV infection process." (PMID 37907581, 2023). "Further, the qRT-PCR assay validated the elevated expression of CmoAP2/ERF during PM infection in the PMR compared with PMS." (PMID 35742978, 2022). "In Siraitia grosvenorii, the expression of AP2/ERF TFs after infection was the most significant compared with that before infection with M. incognita." (PMID 35888092, 2022). "We focused our attention on four TFs families that are known to contribute to environmental stress responses in plants NAC, MYB, bZIP, and AP2/ERF noting that there was between 1.5- to 8-fold increase in gene expression due to PVX-GFP infection." (PMID 33799566, 2021). "In this study, ERF transcription factor was also activated in the BXW-resistant genotype in response to pathogen infection." (PMID 31065041, 2019). "To explore whether AP2/ERF genes respond during infection, we inoculated camphor tree leaves and sampled at the first clearly symptomatic stage, providing a single-time-point snapshot of the transcriptional response." (PMID 40941858, 2025). "In this study, the ERF gene showed an increasing regulation after pathogen infection." (PMID 36740701, 2023). "Studies have shown that the ERF transcription factor family is mainly involved in environmental stress and the hormone stimulation process, such as low temperature stress, hypoxia stress, and pathogen infection process." (PMID 36679048, 2023). "In accordance with other studies that described the relevance of pathways involved in carbohydrate metabolism, we found a high enrichment of the regulons of bHLH, ERF, and unique MTRs that are predicted to participate in negative transcriptional reprogramming for the severe strain infection." (PMID 35682662, 2022).
infection (continued). "Moreover, the CmoAP2/ERF transcript augmentation peaked after 6 h post-infection and started to decline from 24 h to 72 h post-infection in the PMR line." (PMID 35742978, 2022). "To investigate whether the endogenous expression of CmoAP2/ERF expression correlates with different post-infection intervals, we performed qRT-PCR and assessed the CmoAP2/ERF transcript levels in the PMS and PMR lines." (PMID 35742978, 2022). "Moreover, one gene homologous to ERF required for nodulation (ERN3) was downregulated during USDA61 infection." (PMID 33479414, 2021). "Previous studies have demonstrated that infection with Cmm induces expression of ERF TF genes." (PMID 34666675, 2021). "Expression patterns of apple AP2/ERF genes were detected in response to Alternaria alternata apple pathotype (AAAP) infection using RNA-seq with existing data, and the expression of apple AP2/ERF genes was analyzed under NaCl and mannitol treatments using qRT-PCR." (PMID 31988809, 2020). "The expression of PDF1.2, a JA-responsive gene representative of the ERF branch, was significantly induced after infection with B. cinerea both in the WT and the mutant plants, but at 48 hpi, the induction in the ugt80A2;B1 mutant was about twice that in the WT plants." (PMID 31611892, 2019). "ERF proteins involved in defense against pathogen infection have also been extensively documented." (PMID 27916924, 2016). "The decreased level of salicylic acid (SA)-responsive (LOX) and ethylene-responsive (ERF) gene expression in N. benthamiana and A. thaliana supports the notion that ALYs are involved in SA and ethylene-mediated signalling pathways during pathogen infection." (PMID 24723400, 2014). "Before the pathogen infection, plants inoculated with strain PsJN showed partial activity of auxin, ET, brassinosteroids (BR), and JA signaling; as well as regulation of genes related to the cell wall; redox state; peroxidases, signaling, PR proteins and ERF, WRKY and MYB TFs." (PMID 31437216, 2019). "On the other hand, a lower number of DEGs encoding WRKY or AP2/ERF members were observed after infestation by HSt or FDSt in T. friulano, while a significant modulation of genes encoding MYB transcription factors occurred after FDSt infection, both at 3 and 6 dpi." (PMID 31242866, 2019). "Our results indicate that higher PR1 gene and lower ERF genes expression during the first 2 days of root infection correlate with a higher rate of parenchyma colonization and a lower rate of vascular cylinder colonization (infection with the WV strain), and vice versa (infection with the HV strain)." (PMID 25883592, 2015). "Four TF families, the WRKY, NAC, AP2/ERF, and MYB families, that represented a total of 209 master regulator gene candidates induced along infection progress, were distinguished for their central role in FHB responses." (PMID 38443953, 2024). "In Arabidopsis, MYC2 interacted with EIN3 to regulate ERF gene expression and enhance PDF1.2 expression in response to pathogen infection." (PMID 38654166, 2024). "In the current study, we observed a significant upregulation of the RLK, WRKY, AP2/ERF, and MYB families following pathogen infection, suggesting their potential involvement in the response to MR-9 infection." (PMID 37628875, 2023). "Several genes coding for transcription factors (ZIM, JAZ, ERF, AP2, WRKY, NAC) were highly expressed in Syrah healthy berries and upregulated in Trincadeira under infection." (PMID 36479580, 2022). "In this study, we cloned 30 apple AP2/ERF genes, which belonged to the AP2, ERF, DREB, and RAV subfamilies of AP2/ERF, and their changes in expression level in different tissues were analyzed under AAAP infection, and NaCl and mannitol stresses." (PMID 31988809, 2020). "RNA-seq results using previously reported data showed that many members of the apple ERF and DREB subfamilies were induced by Alternaria alternate apple pathotype (AAAP) infection." (PMID 31988809, 2020).
infection (continued). "Genes activated by infection corresponded to transcription factors (e.g., AP2/ERF, MYB, WRKY and NAC) and synthesis of defense-related metabolites, including pathogenesis-related genes, glucosidase and dehydrin." (PMID 31083412, 2019). "Different TFs, i.e., WRKY, NAC, bZIP, and AP2/ERF, etc., have been identified to be differentially expressed in CBB23 after PXO99A infection compared with JG30." (PMID 29498672, 2018). "The AP2/ERF transcription factor ORA59, which was transcriptionally induced in mlo2 mlo6 mlo12 upon infection by G. orontii, acts as a master regulator of JA/ET signaling by integrating both pathways." (PMID 28674541, 2017). "Additionally, during the mid-stage of infection, transcription factors (e.g., WRKY, ERF, and MYB) and genes involved in the MAPK signaling pathway were markedly enriched in ZGB." (PMID 41393875, 2025). "Among them, the first three families with more TFs were bHLH, AP2/ERF-ERF, and WRKY, which may play important roles in the infection of tomato leaves to O. neolycopersici." (PMID 37175940, 2023). "Moreover, several families of transcription factors were also found to be enriched in the set of genes that was upregulated in Trincadeira under infection (ZIM, WRKY, NAC, MYB, JAZ, ERF, and others)." (PMID 36479580, 2022). "Functional analysis of phosphoproteome and transcriptome data confirmed the involvement of these pathways in the EMT during infection, a phenotype that was confirmed in infected cells, along with the essential roles of ERK1/2, ETS1, and ERF activation in C. trachomatis replication." (PMID 35173712, 2021). "The transcription factors such as the C2H2 zinc finger, bZIP (basic domain/leucine zipper), WRKY, AP2 (APETALA2)/ERF (ethylene-responsive factor), NAM/ATAF/CUC(NAC), MYB, MYC and bHLH (basic helix–loop–helix), were significantly altered after viroid infection in plants." (PMID 33005494, 2020). "The expression of many TFs genes including AP2/ERF, MYB, bHLH and WRKY can be induced by a variety of biological and abiotic stresses, such as high salt, drought, low temperature, plant hormones, pathogen infection and so on." (PMID 32635887, 2020). "It has been reported that AP2/EREBP TFs can act as positive regulators as well as negative regulators in resistance to pathogen infection, and the expression levels of several AP2/ERF TFs could be induced or repressed by various biotic stresses as well as abiotic stresses." (PMID 34176023, 2021).
tumor (16 papers, 2017 to 2025). "Capicua (CIC) and ETS2 repressor factor (ERF) loss promote tumor formation and control malignant potential in prostate epithelial cells." (PMID 36383412, 2022). "Interestingly, OE of ERF in mice bearing CIC deficient PC-3 tumor xenografts decreased tumor growth compared to PC-3 parental and PC-3 cells expressing WT CIC (genetic rescue of CIC)." (PMID 36383412, 2022). "Collectively, we have uncovered a molecular subset of PCa defined by a co-deletion of CIC and ERF and further demonstrate a mechanism-based strategy to potentially limit tumor progression through ETV1 inhibition in this subset of human PCa." (PMID 36383412, 2022). "Consistent with our in vitro data, CIC KO increased the tumor growth rate in vivo and genetic reconstitution of WT ERF partially suppressed tumor growth compared to DU-145 CIC KO cells." (PMID 36383412, 2022). "We found that the expression of UGT2B4 was positively associated with expression of multiple well-known oncogenes such as SPINK1, IDH1, MYC, and SRC and negatively associated with expression of well-known tumor suppressors such as CIC and ERF." (PMID 33391440, 2021). "ETS2 is a transcription factor and protooncogene involved in development, apoptosis, and regulation of telomerase; ERF acts as tumor suppressor by binding the protooncogene ETS2 promoter." (PMID 34063511, 2021). "Overexpression of miR-663b promotes cell proliferation and tumor development at an significant level by targeting Ets2-repressor factor (ERF), while upregulating the ERF can eliminate the promotion function of miR-663b." (PMID 34692482, 2021). "Specifically, CDH4, SFRP1, and ERF which are indicated to be tumor suppressor genes by the TSGene 2.0 database and have support from the literature as well; however, our method identified them as monotonically increasing genes." (PMID 33273919, 2020). "The Ets2 repressor factor, ERF, also has tumor suppressor activity in the prostate." (PMID 38317241, 2024). "To further understand if ERF could suppress tumor growth in vivo, we reconstituted WT ERF into CIC proficient and deficient (CIC KO) DU-145 cells and generated subcutaneous xenografts in immunodeficient mice (NU/J)." (PMID 36383412, 2022). "While CIC loss did not enhance colony formation in ERF-deficient DU-145 cells, it significantly increased tumor cell viability, invasion, and migratory capacity compared to control." (PMID 36383412, 2022). "Moreover, genetic reconstitution of ERF into CIC proficient DU-145 cells suppressed the tumor growth rate in vivo." (PMID 36383412, 2022). "Additionally, genetic silencing of both CIC and ERF increased the frequency of subcutaneous tumor xenograft formation in severe-combined immunodeficient (SCID) mice compared to control." (PMID 36383412, 2022). "Sensitive tumours exhibited higher activity of genes involved in energy-coupled mitochondrial transport (P=1 × 10−4), whereas resistant tumours exhibited strong colonic cell features and higher expression of ERF." (PMID 28186126, 2017). "(E) Relative tumor volume in mice bearing DU-145 parental, DU-145 ERF, DU-145 with CIC KO, or DU-145 ERF +CIC KO xenografts (N=10)." (PMID 36383412, 2022). "(H) Bar graph comparing the incidence of PNT2 parental (N=3/10), PNT2 ERF KD (5/10), PNT2 CIC KO (N=5/10), or PNT2 ERF KD+CIC KO (N=6/10) tumor formation in immunodeficient mice." (PMID 36383412, 2022). "Several ETS family members have been shown to act as tumor suppressors within the prostate (EHF, SPDEF, ERF, etc)." (PMID 30603056, 2018). "Functional validation supports the hypothesis that ERF down-regulation leads to activation of the ETS transcriptional program that mediates cell invasion and tumor development." (PMID 28750683, 2017).